IL1B (interleukin 1 beta)
Diseases named in the same sentence as IL1B in open-access papers (continued):
Sharing a sentence is not in itself a finding about the gene and the disease.
colitis (continued). "IFN-γ and IL-1β were significantly reduced in the colitis group compared to those in the controls (p < 0.05)." (PMID 36359214, 2022). "Administration of montelukast (20 mg/kg, i.p.)produced a significant attenuation (p < 0.05) in the levels of the TNF-α and IL-1β in acetic acid-induced colitis." (PMID 36225573, 2022). "Levels of the pro-inflammatory cytokines, TNF-α and interleukin-1b (IL-1b) in the colonic tissue were significantly elevated in both colitis control groups (CTRL+, BSA-NP) compared to untreated control (CTRL–)." (PMID 35214083, 2022). "Mice deficient in the autophagic protein ATG16L1 exhibited a specific increase of Interleukin (IL)-1β and IL-18 in macrophages and severe colitis, which was ameliorated by anti-IL-1β and IL-18 antibody administration." (PMID 35780157, 2022). "The study revealed a high potency of (HT) in suppressing inflammation and alleviating colitis symptoms via downregulation of IL-6, IL-1β, TNF-α, and myeloperoxidase enzyme." (PMID 35990343, 2022). "In a dinitrobenzene sulfonic acid-induced colitis model, guanosine lowered IL-1β, IL-6, and TNF-α mRNA levels and downregulated the expression of NF-κB p65 and the levels of ROS and nitrite." (PMID 36235070, 2022). "Ginseng polysaccharides were demonstrated to alleviate colitis symptoms in rats, accompanied by the downregulation of inflammatory cytokines (IL-1β, IL-2, IL-6, and IL-17)." (PMID 35745651, 2022). "According to the evidence, ATG16L1 deficiency resulted in increased ROS production and impaired mitophagy, which exacerbated colitis in a mouse model through increasing Il-1β expression and TNFα inflammatory factors." (PMID 36499214, 2022). "Konjac oligosaccharide can decrease the levels of malondialdehyde, inducible nitric oxide synthase, TNF-α, and IL-1β in colonic tissues of rats with colitis, and has significant anti-inflammatory effects." (PMID 36033869, 2022). "Similar to human patients, murine colitis models show intense accumulation of Ly6Chi monocytes, which also produce high levels of IL-1β, TNF-α, IL-6, IL-12, and express high level of TREM1 and respond in a highly pro-inflammatory manner to TLR stimulation." (PMID 34912006, 2022). "Similar to ALG, B. animalis and HDCA exerted a strong anti-inflammatory effect in DSS-induced colitis by downregulating inflammatory cytokines (interleukin-1β [IL-1β], IL-6, and tumor necrosis factor alpha [TNF-α])." (PMID 36219101, 2022). "In DSS- and infection-induced mouse models of colitis, dysregulated IL-1β and/or its receptor signaling also promoted exacerbated tissue inflammation." (PMID 35294872, 2022). "Multiple interleukins secreted by lymphocytes mediate their pro/anti-inflammatory effects, and inhibition of proinflammatory cytokines (IL-6, IL-1β, IL-12, and IL-23) is an effective strategy to ameliorate colitis." (PMID 36145301, 2022). "In colitis mice, the mRNA levels of Il-1β (interleukin 1 beta), Ifn-γ (interferon gamma), and Tnf-α (tumor necrosis factor alpha) had increased 3–5 folds in the colon." (PMID 35889745, 2022). "In dextran sodium sulfate (DSS) and infection-induced mouse models of colitis, dysregulated IL-1β, and/or its receptor signaling also promote exacerbated tissue inflammation." (PMID 35294872, 2022). "In particular, beta-glucans significantly decreased colitis clinical symptoms in mice by the downregulation of pro-inflammatory factor expressions such as IL-1β, TNF-α, and IL-6 in the gut." (PMID 36235770, 2022). "The effect of ginseng extracts on IL-1β expression and ROS indicated a possible involvement of inflammasomes in the anti-colitis function." (PMID 36090968, 2022). "Previous studies on mouse colitis have found that IL-1β is significantly increased when intestinal inflammation occurs, which mediates chronic intestinal inflammation by promoting the accumulation of IL-17A-secreting innate lymphoid cells and Th17 cells." (PMID 35265068, 2022).
colitis (continued). "Reports are suggesting that IL-1β and IL-18 induced by the NLRP3 inflammasome confer protection against colitis and colitis-associated tumorigenesis." (PMID 36389791, 2022). "To further assess the effect of LBGH on DSS-induced colitis in mice, we measured the levels of pro-inflammatory cytokines including IL-1β, IL-6, and TNF-α in serum as well as in colonic tissue through ELISA kits." (PMID 36033869, 2022). "Our results showed that Bp7 and Bp8 intervention obviously reduced the colonic TNF-α and IL-1β levels and significantly elevated the colonic IL-10 levels, indicating that Bp7 or Bp8 effectively relieved the development of inflammation in colitis mice." (PMID 35681301, 2022). "In previous studies, we observed an increase in IL-1β production from colonic DCs in acute colitis-induced Prdm1-CKO mice." (PMID 35674135, 2022). "First of all, the JW formula efficaciously alleviated the inflammatory reactions during the progression of colitis, as evidenced by the decreased IL-1b and TNFα levels in the serum of colitis mice after the JW therapy." (PMID 36091591, 2022). "TNF-α, IL-6, IL-1β, and IL-2 are involved in many inflammatory visceral pain diseases like visceral pain after colitis, surgery, and endometriosis." (PMID 35642022, 2022). "DSS-induced colitis is associated with NLPP3 inflammasome activation and excessive IL-1β production." (PMID 36552376, 2022). "The results showed that, compared with the control group, the levels and expression of pro-inflammatory factors TNF-α, IL-1β, and IL-6 in colon tissues from colitis mice were significantly increased." (PMID 35387334, 2022). "During active ulcerative colitis, IL-1β, one of the most prominent mediators of colon inflammation, is secreted in greater quantities." (PMID 35428860, 2022). "CP-25 regulated macrophage polarization from a M1 to a M2 phenotype to attenuate DSS-induced colitis and inhibited IL-1β and IL-18 production in mice." (PMID 36457713, 2022). "NK151, NK173, and NK175 alleviated iGm-induced colitis: they decreased IL-1β and IL-6 expression, while IL-10 and claudin-1 expression increased." (PMID 35631220, 2022). "A recent study found that there is an upregulation of intestinal IL-1β in melanoma patients treated with CICB who developed high-grade colitis." (PMID 35432346, 2022). "L-fucose is found to decrease elevated levels of TNF-α, IL-1β, and IL-6 in serum and colonic tissues of mice with a model of colitis." (PMID 36421993, 2022). "It has been shown that RA inhibits the induction of iNOS and COX-2 expression and production of pro-inflammatory cytokines such as IL-6, IL-22 and IL-1β in DSS (dextran sulphate sodium)-induced colitis in the mouse model." (PMID 35079027, 2022). "During the pathogenesis of DSS-induced colitis, we investigated the expression of the proinflammatory cytokines IL-6, IL-1β, and TNF-α, which are abundantly recruited in mice during DSS-induced colitis." (PMID 36187993, 2022). "NF-κB/p65 possesses the role as a “master regulator” of inflammation and aggravates colitis by promoting the expression of inflammatory cytokines (IL-1β, TNF-α, etc.)." (PMID 35126813, 2022). "We also found that mEVs decreased the expression of pro-inflammatory factors (IL-1β, IL-6 and IL-17A) in colitis." (PMID 35893911, 2022). "FMT significantly alleviated DSS-induced colitis and decreased immune cell infiltration in colon tissue, and inflammatory factors expression of IL-1β, TNF-α and IL-17a." (PMID 36578000, 2022). "Others showed inhibiting IL-1β or caspase-1 effectively improved intestinal inflammation in colitis model." (PMID 35320937, 2022). "Lactobacillus acidophilus treatment can also alleviate the severity of DSS-induced colitis and inhibit pro-inflammatory cytokines in the colon, such as IL-1β、 IL-6、IL-17, and TNF-α." (PMID 36189293, 2022).
colitis (continued). "Depression increased the Enterococcaceae population, NF-κB+/Iba1+ cells, expression of IL-1β and IL-6, in IBD patients, which cause more severe colitis with a disrupted intestinal barrier, and accelerated the translocation of fecal LPS into the blood." (PMID 36275694, 2022). "Along with this, mature IL-1β production was also significantly upregulated in our mouse model of DSS-induced colitis." (PMID 35784693, 2022). "A number of studies have shown that blockade of IL-1β or IL-1R signaling using antibodies can effectively ameliorate colon inflammation in Crohn’s disease and mouse model of colitis." (PMID 36090968, 2022). "Our previous study also showed that IL-1β was highly expressed in colitis mice after periodontitis salivary microbiota gavage." (PMID 36034700, 2022). "A prior study suggested that the elevation of colonic TNF-α, IL-6, and IL-1β levels in colitis mice were induced by DSS, which is consistent with our findings." (PMID 35681301, 2022). "The mRNA expression levels of TNF-α, IL-6, and IL-1β in colon tissue of the DSS-induced colitis group were considerably elevated by the 4% DSS treatment." (PMID 36080669, 2022). "In our study, except for TNF-α, other pro-inflammatory factors such as IL-6 and IL-1β were also vastly increased in TNBS-induced colitis." (PMID 35571126, 2022). "We also observed that DSS‐induced colitis in Il34−/− rats led to increased levels of pro‐inflammatory cytokines Il6, Il1b, Il22 and a trend for an increase for Il17a, all involved in gut inflammation, whereas Ifng was decreased." (PMID 36030499, 2022). "T. halophilus administration significantly downregulated IL-1β levels in colitis mice (7.65 ± 1.35 pg/mL vs. 18.21 ± 3.01 pg/mL, p < 0.05) compared to untreated colitis mice." (PMID 35741032, 2022). "Overexpression of NF-κB induces the hyperactivation of inflammatory response and promotes the release of proinflammatory cytokines (containing TNF-α, IL-6, and IL-1β), even facilitating the occurrence of colitis." (PMID 35681301, 2022). "Dysfunction of the colonic epithelial barrier can also promote the occurrence and development of colonic inflammation, with pro-inflammatory cytokines such as IL-1β, IL-6 and TNF-α playing a key role in the development of inflammation." (PMID 35514335, 2022). "The secondary BAs consistently showed a significant reduction in the mRNA levels of pro-inflammatory cytokines (Il6, Il1β, Tnfα) and some monocytes-related chemokines (Ccl2, Ccl7, Ccl8) in colitis mice." (PMID 36050867, 2022). "Our study showed that MNS administration significantly relieved mouse colitis and decreased IL-1β secretion and macrophage infiltration." (PMID 35784693, 2022). "Recent studies reported that DSS colitis severity is associated with increased production of various inflammatory mediators such as TNF-α, IL-1β, and MPO activity; and IL-10 and TGF-β drive anti-inflammatory response to prevent colitis." (PMID 36193153, 2022). "Various cytokines play important roles in colitis, in which IL-1β and TNF-α are important inflammatory cytokines and were expressed abundantly during the period of colitis." (PMID 36499169, 2022). "The oral administration of thinned apple polyphenols attenuated gene expression of IFN-γ, TNF-α, IL-1β, IL-6, IL-17, and IL-22 in the colons of mice with colitis." (PMID 35741912, 2022). "Oral administration of NK151, NK175, or their (4:1) mix suppressed cGm-induced colitis in mice: they suppressed colonic myeloperoxidase activity, IL-1β and IL-6 expression, and the NF-κB+CD11c+ cell population, while significantly increasing IL-10 expression." (PMID 35631220, 2022). "This beneficial effect was reported to be mediated through the inhibition of TLR4-NF-κB-NLRP3 axis and, consistently, the pro-inflammatory cytokines (tumoral necrosis factor-α (TNF-α), IL-1β, IL-6, IL-2) levels were also suppressed in the treated colitis mice." (PMID 36558455, 2022).
colitis (continued). "Higher levels of pro-inflammatory cytokines including TNF-α, IL-1β, and IL-6 and lower levels of anti-inflammatory cytokine IL-10 were found in colitis mice when compared with the control group." (PMID 35911761, 2022). "GM-CSF augments MФ activation towards inflammatory signals (i.e. expressing IL-1β, IL-12/23) during colitis in both humans and mice." (PMID 36189323, 2022). "The expression of TNF-α, IL-6 and IL-1β was substantially upregulated in DSS-induced colitis mice, and treatment with PNU-282987 significantly reduced the enhancement." (PMID 36058917, 2022). "IFN-γ and IL-1β levels were significantly higher in the intestinal mucosa of SI-treated mice than in the mice of the colitis group (p < 0.05)." (PMID 36359214, 2022). "In contrast, the levels of TNF-α, IL-6, and IL-1β were increased considerably, indicating that colon inflammation was induced in mice after DSS treatment." (PMID 36359970, 2022). "B. bifidum BGN4-SK significantly ameliorated the symptoms of DSS-induced colitis, increased the expression of tight junction genes (claudin and ZO-1), and decreased pro-inflammatory cytokines IL-6, IL-1β and TNF-α." (PMID 35672695, 2022). "IL-1β and IL-6 are two important pro-inflammatory factors positively correlated with colonic inflammation." (PMID 35684007, 2022). "IFN-I signaling protects in DSS-induced colitis models through suppression of pro-inflammatory cytokine production, including IL1β." (PMID 35055106, 2022). "Frequencies of CD8+NK1.1+ cells decreased in mice with colitis after T. halophilus treatment and IL-1β levels were also reduced." (PMID 35741032, 2022). "It was remarkable that rats that suffered from DSS-induced colitis had the highest expression levels of pro-inflammatory cytokines IL-6, IL-1β and TNF-α and anti-inflammatory IL-10 levels." (PMID 35745756, 2022). "YST from low dose to high dose gradually decreased the levels of TNF-α, IL-1β, and IL-6 in colon tissues of colitis mice." (PMID 34055024, 2021). "Intraperitoneal injection of LPS induced colitis: it induced colon shortening, IL-1β, IL-6, and TNF-α expression and suppressed IL-10 expression in the colon." (PMID 33985438, 2021). "Cytokines related to colitis pathology (such as IL-6, IL-1β, IFNγ, and IL-17a) are significantly inhibited in the colon tissue of exosome-treated model mice." (PMID 34683937, 2021). "Lactic acid and SyBE also significantly reduced the contents of pro-inflammatory cytokines, such as TNF-α, IL-6, and IL-1β, in serum, that promote the development of colitis." (PMID 34899735, 2021). "The latest experimental and clinical data show that pro-inflammatory cytokines such as TNF-α, IL-1β and IL-6 play an important role in the pathogenesis of colitis." (PMID 34551815, 2021). "In previous studies on salt and colitis in mice, high salt showed an increased expression of IL-1β and TNF-α in the colon." (PMID 34066160, 2021). "Increased expression of epithelial GSDMD is observed in patients with IBD and experimental colitis model animals, and the epithelial-derived GSDMD mediates the release of insoluble IL-1β during experimental colitis." (PMID 34683937, 2021). "Mice that were fed American ginseng showed a significant improvement in DSS-induced colitis symptoms, and had reduced levels of the pro-inflammatory cytokines IL-1β and IL-6." (PMID 34073220, 2021). "Intriguingly, the high expression level of β-catenin was in accordance with the powerful immunoregulatory ability of IL-1β-primed ERCs in colitis." (PMID 34090510, 2021). "The possible reason is that IL-1β is involved in repairing IECs and reconstituting epithelial barriers during colitis, which is consistent with previous report." (PMID 34721422, 2021). "IL-1β is a critical proinflammatory cytokine produced by the inflammasome, and its role in colitis remains controversial." (PMID 34721422, 2021).
colitis (continued). "Further, colitis induced lipid peroxidation, neutrophil infiltration, and expression of pro-inflammatory cytokines (IL-1β and TNF-α) decreased in both models." (PMID 34067499, 2021). "Treatment with Cardamonin reduces the secretion of IL-1β and TNF-α in patients with recurrent colitis and colitis-associated tumors and inhibits cell viability and the production of inflammatory cytokines in colorectal cancer cells in vitro." (PMID 34539403, 2021). "Some reports found that IL-1β enhanced colitis severity in animal models, while others reported that Il1β-/- and Il1r1-/-, the IL-1α and IL-1β receptor, mice displayed exacerbated severity in DSS-induced colitis." (PMID 34721422, 2021). "Reduced IL-1β levels result in amelioration of injury and improvement of clinical and histological signs of colitis." (PMID 33672304, 2021). "Using ELISA, we also found the expression levels of the pro-inflammatory cytokines TNF-α, IL-6, IFN-γ, and IL-1β were increased in PBLDIEC−/− mice versus WT mice with DSS-induced colitis." (PMID 34059646, 2021). "IL-1β and IL-6 have been elucidated as potent pro-inflammatory cytokines that stimulate several immune cells in colitis conditions." (PMID 33802855, 2021). "In a model of DSS-induced colitis, Olfr78 KO mice showed higher levels of intestinal inflammation and altered expression of immune related- and inflammatory genes, including that of the cytokine IL-1β, known for its key role in colitis." (PMID 33807994, 2021). "Some studies have shown that NLRP3 inflammasome-induced IL1β aggravates colitis, and inhibition of NLRP3 inflammasome activity has been proposed as a therapeutic strategy for treatment of colitis." (PMID 34075172, 2021). "PET imaging and ex vivo analysis revealed that in DSS colitic mice, distal colonic uptake of 89Zr-a-IL-1b was increased compared to control mice and correlated with colitis severity." (PMID 34298967, 2021). "before and during the DSS treatment ameliorated the severity of colitis and reduced the colonic pro-inflammatory cytokine IL-1β." (PMID 35223407, 2021). "It was found that serum TNF-α, IL-6, IL-18 and IL-1β levels in DSS induced colitis mice model was significantly higher than those in the control normal group." (PMID 34628369, 2021). "As TNFα, IL-1β, and IL-6 play crucial roles in the pathogenesis of colitis and cinacalcet suppressed the production of those inflammatory cytokines, we assessed the anti-inflammatory effect of cinacalcet on DSS-induced colitis." (PMID 34880751, 2021). "It was found that IL-1β-primed ERC treatment markedly attenuated colonic damage, body weight loss, and colon length shortening in colitis mice." (PMID 34090510, 2021). "Oral administration of acacetin increased the production of iNOS, COX-2, IL-6, TNF-α and IL-1β in mice with DSS-induced colitis." (PMID 33806061, 2021). "Taken together, these results suggested that IL-1β-primed ERCs exhibited anti-inflammatory effects in colitis through reducing DKK1 sections, which in turn leads to the activation of Wnt/β-catenin signaling." (PMID 34090510, 2021). "ER stress plays a key role in human diseases, including colitis and acute pancreatitis, by increasing the release of proinflammatory factors such as IL-1β, cleaved caspase-1, and TNF-α which is elicited by TXNIP during neuroinflammation." (PMID 34790063, 2021). "FMT, which involves the exogenous manipulation of the gut microbiota, inhibited the inflammation-induced increase in colonic Il1b expression in a mouse model of DSS-induced colitis." (PMID 33578830, 2021). "Compared with the DSS induced colitis mice model group, administration of Schisandrin B more significantly reduced the serum TNF-α, IL-6, IL-18 and IL-1β levels in DSS induced colitis mice model." (PMID 34628369, 2021). "The inhibition of ERK can also reduce the production of IL-23 and IL-1β and reduce the symptoms of autoimmune diseases such as demyelinating diseases, colitis, and rheumatoid arthritis." (PMID 34691022, 2021).